GDNF (glial cell derived neurotrophic factor)
Diseases named in the same sentence as GDNF in open-access papers (continued):
Sharing a sentence is not in itself a finding about the gene and the disease.
schizophrenia (continued). "Our data replicated this finding, although a report showed differences in BDNF levels between patients with schizophrenia and healthy controls, rather than GDNF levels." (PMID 39886050, 2024). "There have been no previous studies exploring the effect of CRT on GDNF levels in patients with schizophrenia, leaving the relationship between serum neurotrophic factors and CRT unclear." (PMID 39886050, 2024). "Despite these multiple lines of suggestive evidence, functional analysis linking GDNF signalling to schizophrenia is currently lacking." (PMID 35618883, 2022). "Serum levels of BDNF, GDNF and NGF in schizophrenia patients have been evaluated previously." (PMID 34763683, 2021). "BDNF, GDNF, NGF and Klotho levels were lower in schizophrenia patients than in healthy controls." (PMID 34763683, 2021). "In sum, the relationship between GDNF levels and the pathogenesis of schizophrenia has not yet been sufficiently investigated, and therefore new studies are needed." (PMID 34763683, 2021). "In this study, the hypothesis that the blood serum levels of BDNF, GDNF, NGF and Klotho in schizophrenia patients and healthy controls would be related to cognitive functions was investigated." (PMID 34763683, 2021). "The level of GDNF in participants with video game training increased, and the levels of Tau, MIP-1 and MIP-4 decreased, which may be used as serum markers to evaluate the cognitive function of patients with schizophrenia." (PMID 40251163, 2025). "Our results on the increase in GDNF in schizophrenia do not agree with the literature data." (PMID 37239308, 2023). "In dopamine neurons, GDNF mainly signals via RET receptor, suggesting that RET inhibitors such as Selpercatinib and Pralsetinib, currently used in cancer therapy, may carry potential to treat a subgroup of patients with schizophrenia." (PMID 35618883, 2022). "Except for a significant and negative correlation between CSF GDNF and VEGF receptor 1 levels in patients with schizophrenia (r = –0.26, p = 0.013), there were no proteins that showed a significant and negative correlation." (PMID 32439851, 2020).
pancreatic cancer (32 papers, 2005 to 2026). "GDNF accelerates the migration of Kras-mutated pancreatic cancer cells to nerve cells through the RET–phosphatidylinositol 4,5-diphosphate-3-kinase catalytic pathway." (PMID 39119085, 2024). "Overexpression of GFRα1 dramatically restores cellular growth in APE1-deficient pancreatic cancer cells treated with GDNF." (PMID 32438692, 2020). "GDNF treated pancreatic cancer cell line displayed silk foot and tablet lipid formation enhanced extracellular matrix proteins adhesion ability, which played an important role in the PDAC-related PNI." (PMID 39119085, 2024). "The RET protein tyrosine kinase receptor for GDNF is overexpressed in human neuroplexi tissues and is present in several pancreatic cancer cell lines." (PMID 39346791, 2024). "used siRNA library screening and found that the GDNF–RET–βPix–Cdc42 pathway guided the migration of pancreatic cancer cells to nerve cells." (PMID 39119085, 2024). "- Implicated in tumorigenesis; promotes the growth and metastasis of various cancers, including neuroblastoma and pancreatic cancer.- GDNF can stimulate angiogenesis and enhance the invasive properties of cancer cells." (PMID 38375479, 2024). "In a tumor-inflammatory environment, pancreatic cancer cells upregulate GDNF release by activated macrophages following LPS stimulation." (PMID 37958856, 2023). "Our study finds that after rhNodal treatment, neurotrophins (NGF, BDNF, and GDNF) significantly increased in pancreatic cancer cells, and vice versa." (PMID 35126957, 2022). "RET alterations occur in ~1.9% of pancreatic cancers whereas wild-type RET, co-receptor GFRα1, and GDNF are overexpressed in 50-70% of pancreatic cancer cases." (PMID 35957881, 2022). "The results illustrate that Nodal upregulates NGF (nerve growth factor), BDNF (brain-derived neurotrophic factor), and GDNF (glial cell line-derived neurotrophic factor) expression in pancreatic cancer cells and promotes cancer cell migration/invasion." (PMID 35126957, 2022). "Previous studies of GDNF and its receptors in perineural invasive tumors have focused on pancreatic cancer, cholangiocarcinoma, and other hepatobiliary tumors." (PMID 33628594, 2021). "In this study, we demonstrate that GDNF/GFRα1 trigger cell proliferation via the Src/ERK pathway in pancreatic cancer cells." (PMID 32438692, 2020). "Taken together, APE1-induced GFRα1 allows pancreatic cancer cell proliferation through RET/Src/ERK cascade signaling in the response to GDNF." (PMID 32438692, 2020). "Our study demonstrates that APE1 functions as a modulator of the GDNF/GFRα1/Src/ERK cascade during pancreatic cancer cell proliferation." (PMID 32438692, 2020). "In pancreatic cancers, GDNF/GFRα1/RET is expressed more robustly than in normal pancreatic tissue and benign tumors." (PMID 32438692, 2020). "Glial cell line-derived neurotrophic factor (GDNF) has been shown to upregulate MMP-9 in pancreatic cancer suggesting a supportive function in tumor invasion." (PMID 32092997, 2020). "We demonstrated a novel regulatory mechanism for GDNF/GFRα1/RET/Src axis by APE1 in pancreatic cancer cell growth." (PMID 32438692, 2020). "Here, we demonstrate that APE1 accelerates pancreatic cancer cell proliferation through glial cell line-derived neurotrophic factor (GDNF)/glial factor receptor α1 (GFRα1)/Src/ERK axis-cascade signaling." (PMID 32438692, 2020). "In pancreatic cancers, increased levels of neurotrophic factors including GDNF have been described, and these are mainly secreted from intrapancreatic and extrapancreatic nerves." (PMID 32438692, 2020). "The G691S RET polymorphism was reported to enhance the response of RET to glial cell line-derived neurotrophic factor (GDNF) and was correlated with the aggressive phenotype of pancreatic cancers and cutaneous malignant melanomas." (PMID 32293499, 2020). "We demonstrate that APE1 also stimulates pancreatic cancer cell proliferation via a GDNF/GFRα1/Src/ERK signaling pathway in this study." (PMID 32438692, 2020).
pancreatic cancer (continued). "MIA PaCa-2 human pancreatic cancer cells, which contain endogenous APE1, were treated with GDNF, a binding partner of GFRα1 to investigate the effect of GDNF on pancreatic cancer cell proliferation." (PMID 32438692, 2020). "The proliferation of endogenous APE1 expressed-MIA PaCa-2, a human pancreatic carcinoma cell line, was increased by treatment with GDNF, a ligand of GFRα1." (PMID 32438692, 2020). "GDNF has been reported to promote tumor cell invasion in pancreatic cancer cell lines, and GDNF is strongly expressed in intrapancreatic nerves." (PMID 22745701, 2012). "Glial cell line-derived neurotrophic factor (GDNF) is a chemoattractant for pancreatic cancer cells in the processes of tumor progression, migration and invasion." (PMID 22920886, 2012). "As a ligand for the RET proto-oncogene, GDNF would be a likely candidate for promoting cancer progression, and has been proposed to do so in pancreatic cancer." (PMID 18616821, 2008). "Similarly, perineural invasion of pancreatic cancer involves endoneurial macrophages secreting GDNF and activating RET tyrosine kinase receptor, a GFRA1 coreceptor." (PMID 38962317, 2024). "Moreover, enhanced secretion of GDNF by cells within the tumor microenvironment stimulates RET activity in pancreatic tumor cells, thus exerting a paracrine effect on pancreatic cancer cells to drive perineural invasion." (PMID 35957881, 2022). "GDNF is related to the degree of pain in patients with pancreatic cancer." (PMID 35126957, 2022). "Intriguingly, GFRα1 overexpression by GFRα1-encoded lentivirus restored GDNF-stimulated cell proliferation in APE-deficient pancreatic cancer cells, indicating that APE1 promotes GDNF-dependent pancreatic cancer cell proliferation by regulating GFRα1 expression." (PMID 32438692, 2020). "Moreover, GDNF induces perineural invasion in pancreatic cancers, and inhibition of RET signaling suppressed perineural invasion." (PMID 22745701, 2012). "In addition, GDNF/GFRα1 signaling is detected in pancreatic cancers." (PMID 32438692, 2020). "In pancreatic cancer cell lines, glucose concentration tends to alter the cell proliferation in a concentration dependent manner through the expression of GDNF (glial cell line derived neurotrophic factor) and RET (tyrosine kinase receptor)." (PMID 40735043, 2025). "Glial cell line-derived neurotrophic factor (GDNF) and integrins contribute to invasion and metastasis in human pancreatic cancer cells." (PMID 37566075, 2023). "Western blot analysis was used to evaluate NGF, BDNF, GDNF, and MMP-9 protein expression in pancreatic cancer cells." (PMID 35126957, 2022). "For example, silencing circFOXK2 significantly inhibited pancreatic cancer progression and elevated miR-942 expression, eventually indirectly suppressed expression of PAX6 and GDNF." (PMID 34906151, 2021). "For example, exposure of dorsal root ganglia to 4 Gy of single fraction radiation significantly reduced GDNF expression and inhibited PNI in co-cultures with pancreatic cancer cells." (PMID 34885121, 2021). "GFRα1 and GDNF triggers Ret/Src/ERK activation, resulting in the increased growth of pancreatic cancer cells." (PMID 32438692, 2020). "A positive correlation was observed among the expression levels of NGF, p75NTR, TRKA, TRKB, glial cell line-derived neurotrophic factor (GDNF), and PNI in pancreatic cancer tissues or cell lines." (PMID 33392191, 2020). "For instance, GDNF and other members of the GDNF family (artemin, NRTN and persephin) were shown to play important cancer promoting roles in pancreatic cancer." (PMID 33142779, 2020). "Additionally, endoneurial macrophages that lie around nerves may also foster the invasion of pancreatic cancer cells along the nerves through secreting high levels of glial-derived neurotrophic factor (GDNF), thus inducing the activation of the GNDF receptor GFRα1 and its co-receptor RET." (PMID 27191744, 2016).
pancreatic cancer (continued). "Additionally, neurotrophins, including nerve growth factor (NGF), brain-derived neurotrophic factor (BDNF), glial cell line-derived neurotrophic factor (GDNF), and chemokines and neurotransmitters exert various effects in regulating PNI in pancreatic cancer." (PMID 35449152, 2022). "Similarly, delivering 8 Gy of radiation to the sciatic nerve of mice reduced GDNF expression, decreased PNI, and preserved nerve function in mice implanted with pancreatic cancer cells." (PMID 34885121, 2021). "Our results highlight a critical role for APE1 in GDNF-induced pancreatic cancer cell proliferation through APE1/GFRα1/Src/ERK axis-cascade signaling and provide evidence for future potential therapeutic drug targets for the treatment of pancreatic cancer." (PMID 32438692, 2020). "Taken together, these results indicate that Src may be an important intermediary between GDNF/GFRα1 and ERK signaling through APE1-mediated pancreatic cancer cell proliferation." (PMID 32438692, 2020). "In this study, we found that despite GDNF treatment, pancreatic cancer cell proliferation did not occur without GFRα1 expression which is induced by APE1." (PMID 32438692, 2020). "Furthermore, many soluble factors of neurotrophic or axon-guiding nature such as NGF, brain-derived neurotrophic factor (BDNF), neurotrophin 3 (NT-3), glial-cell-derived neurotrophic factor (GDNF), neurturin, artemin, sonic hedgehog, SEMA3D, and others are overexpressed by pancreatic tumour cells." (PMID 35269454, 2022).
Cognitive impairment (31 papers, 2013 to 2026). Abnormal cognition is characterized by deficits in thinking, reasoning, or remembering. "But we found that lower serum levels of GDNF were associated with more severe cognitive impairment in attention distribution and verbal fluency in first-episode schizophrenics in our previous study." (PMID 31420036, 2019). "GDNF levels were shown to be strongly associated with cognitive impairment (P < 0.001)." (PMID 35360515, 2022). "After reviewing the cognitive status, we found that PD‐high‐GDNF subjects tended to have mild cognitive impairment." (PMID 37718594, 2024). "Nonetheless, it is elusive if the pattern of brain topological connectivity differed across PD with divergent serum GDNF levels, and the accompanying profile of cognitive deficits has yet to be determined." (PMID 37718594, 2024). "GDNF and miR-29a-3p are promising as biomarkers for understanding and addressing cognitive deficits in psychosis." (PMID 38645418, 2024). "Cognitive deficits are associated with altered levels of several neurological factors, such as brain-derived neurotrophic factor (BDNF), nerve growth factor (NGF), and glial cell-derived neurotrophic factor (GDNF)." (PMID 36329874, 2022). "The exogenous expression of GDNF in the astrocytes of aged rats was able to improve their cognitive deficits, and GDNF administration had a protective role against AD-like changes in animal models." (PMID 36291068, 2022). "The more serious cognitive impairment with the lower levels of GDNF and four cognition-related neurotransmitters including dopamine metabolites homovanillic acid (HVA), acetylcholine (Ach), γ-aminobutyric acid (GABA), and 5-hydroxytryptamine (5-HT)." (PMID 35360515, 2022). "The increase in GDNF in aged hippocampus showed an increase in learning and memory functions, while the decreased GDNF showed cognitive impairment." (PMID 35360515, 2022). "In patients with mild cognitive impairment and Alzheimer's disease, decreased peripheral serum GDNF levels have been observed." (PMID 35095724, 2021). "NBP was protective against hippocampal neuron apoptosis, and this was associated with regulation of GDNF/GFRα1/Ret and AKT/ERK1/2 signaling pathways, thus reducing cognitive impairment." (PMID 31456664, 2019). "Our results indicate that lower GDNF serum levels in DS patients are related to more severe cognitive impairments in executive function and attention." (PMID 31420036, 2019). "Meanwhile, we would like to evaluate the relationship between BDNF or GDNF levels and cognitive impairment in DS." (PMID 31420036, 2019). "Any changes or alterations of neurotrophic factor level such as BDNF, NGF, and GDNF are related to cognitive deficit or impairment." (PMID 29200666, 2017). "In contrast, patients with PD‐low‐GDNF tended to have moderate cognitive impairment." (PMID 37718594, 2024). "In our study, a relative fold change of 6.2 in GDNF gene expression by real-time PCR strengthens this association and the fold drop of 5.51 in ASD patients can be considered a diagnostic and therapeutic marker for cognitive deficit in ASD." (PMID 39502974, 2024). "Given the significant correlation characteristics of the serum GDNF and DC values within the PD group, we speculate that combined detection can improve the accuracy of screening for the cognitive impairment of PD patients." (PMID 37718594, 2024). "This study was based on a clinical case–control study to investigate whether serum GDNF level is related to the occurrence of PD‐CI and which domain of cognitive impairment is most closely related." (PMID 37718594, 2024). "Early identification of changed GDNF expression may enable prompt and focused therapy interventions, therefore slowing the development of behavioral and cognitive deficits in ASD patients." (PMID 39502974, 2024). "Combining serum GDNF levels, PD duration, and education levels could be used to distinguish the degree of cognitive impairment." (PMID 37718594, 2024).
Cognitive impairment (continued). "GDNF-mediated hippocampal neurogenesis contributed to the rescue of the cognitive impairment, an enhanced functionality of the antioxidant mechanisms protecting from the oxidative stress also against cognitive deficit." (PMID 35360515, 2022). "The study discovered that GDNF levels fell considerably in people with cognitive impairment, implying that GDNF may have a role as a disease biomarker." (PMID 35360515, 2022). "Our results identify endogenous GDNF as a potential modulator of cholinergic transmission and call for future studies on endogenous GDNF function in neurodegenerative disorders characterized by cognitive impairments, including AD, LBD, and PDD." (PMID 34475820, 2021). "According to one of our studies, low serum GDNF levels predict cognitive impairment in PD." (PMID 35095724, 2021). "This combination of Chinese and Western drug therapy decreased the seizure severity and SRS frequency, markedly improved cognitive impairment and significantly decreased neuronal damage by up-regulating the expression of GDNF proteins and the level of Bcl-2/Bax in the hippocampal CA3 region." (PMID 29560767, 2018). "Understanding the mechanisms by which GDNF modulates neuronal functioning and protects against cognitive decline may provide insights into the pathophysiology of psychosis and lead to the development of novel therapeutic strategies for cognitive disorders." (PMID 38645418, 2024). "The changes in BDNF, GDNF and IGF-II in both groups may be related to several variables including the intensity and duration of the intervention, timing of measurement, genetic polymorphism and cognitive impairment, which may be clarified in future studies." (PMID 36556107, 2022). "Therefore, the decrease in GDNF induced by CO exposure may be involved in cognitive impairment by affecting neurons." (PMID 33737717, 2021). "Our results also confirm that GDNF enhances DA signaling in the PFC and ameliorates cognitive impairment in PD mice." (PMID 39090173, 2024). "The findings are consistent with previous research indicating that GDNF and miRNA-29a may be involved in neuronal plasticity, suggesting that further research on their effects on neuronal functioning may lead to the development of novel therapeutic strategies for cognitive disorders in psychosis." (PMID 38645418, 2024). "This study demonstrated that METH-induced cognitive impairment was significantly improved by administration of BER, possibly by promoting the expression of neurotrophins in the hippocampus, including BDNF and GDNF." (PMID 36594063, 2023). "Engineering hematopoietic stem cells to deliver glial cell line derived neurotrophic factor (GDNF) directly to sites of neurodegeneration in mouse models of PD to mitigate decline in motor function, comorbid cognitive impairment and depressive-like behaviors." (PMID 34205235, 2021). "The present research showed that lithium prevented cognitive impairment through reestablishment of BDNF, NGF, and GDNF expression." (PMID 29200666, 2017). "The idea is that cognitive deficits in AD are related to change of BDNF blood level as well as that of other neurotrophic factors such as the nerve growth factor and GDNF in blood." (PMID 28289378, 2017). "Our results suggest that GDNF ameliorated the defect of DAT glycosylation modification to increase its membrane distribution by enhancing Golgi aggregation, followed by the enhancement of DA signaling, and ultimately ameliorating cognitive impairment in PD." (PMID 39090173, 2024). "Recent studies have shown that high levels of serum/plasma α-Syn and low levels of serum glial cell line-derived neurotrophic factor (GDNF), miRNA-29s (miR-29s), vitamin D, and 25-hydroxyvitamin D may be involved in the cognitive impairment of PD-MCI and PDD patients." (PMID 34912207, 2021).